CAD (carbamoyl-phosphate synthetase 2, aspartate transcarbamylase, and dihydroorotase)
Diseases named in the same sentence as CAD in open-access papers (continued):
Sharing a sentence is not in itself a finding about the gene and the disease.
epilepsy (4 papers, 2021 to 2025). A brain disorder characterized by episodes of abnormally increased neuronal discharge resulting in transient episodes of sensory or motor neurological dysfunction, or psychic dysfunction. "Our case uniquely demonstrates a relatively late‐onset case of refractory epilepsy in the setting of a homozygous variant in the CAD gene, with a striking, rapid response to replacement therapy." (PMID 33249780, 2021).
liver cancer (4 papers, 2020 to 2025). An epithelial or non-epithelial malignant neoplasm that arises from the liver. "Stimulation of β-catenin/AKT2/CAD signaling cascade on pyrimidine synthesis is an essential and druggable vulnerability for β-catenin mutant liver cancer." (PMID 36122209, 2022). "As a transcriptional activator of AKT2, β-catenin potentiates AKT2 phosphorylation of CAD, which in return stimulates de novo pyrimidine synthesis and liver cancer development." (PMID 36122209, 2022).
bladder cancer (3 papers, 2018 to 2023). "However, supporting our findings, a positive correlation of l-CaD expression with in vitro migration and invasion is reported in myoblasts, HeLa, bladder cancer, and osteosarcoma cells." (PMID 37573448, 2023). "Of note, we found that ERCC2 alterations (which are recurrently found in bladder cancer) co-occur significantly with POLD2 expression (P = 0.010; data not shown), but not with CAD expression, suggesting POLD2 as putative gene of interest in future studies examining ERCC2." (PMID 30038717, 2018).
infantile epileptic encephalopathy (3 papers, 2019 to 2022). an epileptic condition characterized by epileptiform abnormalities associated with progressive cerebral dysfunction. "Type 50 early infantile epileptic encephalopathy, or EIEE-50 for short, is an autosomal recessive genetic disorder resulting from CAD mutations." (PMID 35356445, 2022). "Biallelic variants in the multienzyme complex CAD (carbamoyl phosphate synthetase 2, aspartate transcarbamylase, and dihydroorotase, CAD, MIM #616457) have recently been reported to lead to a progressive early infantile epileptic encephalopathy with dyserythropoietic anemia and tetraparesis." (PMID 30681159, 2019).
neuroblastoma (3 papers, 2021 to 2022). Neuroblastoma (NB) is the most common solid, extracranial childhood tumor. "This strong intercorrelation between CAD, DHODH, and UMPS was also evident in the subset of neuroblastoma cell lines." (PMID 35943801, 2022). "All these reactions in purine and pyrimidine nucleotide synthesis are catalyzed by glutamine amidotransferases (PPAT, PFAS, GMPS, CAD, and CTPS1/2), which are transcriptionally activated by MYCN in neuroblastoma cells." (PMID 36077650, 2022).
prostate carcinoma (3 papers, 2012 to 2023). A carcinoma that arises from epithelial cells of the prostate gland. "Tumor-specific CaD splice variants have been reported in tissues from patients with colon, urinary bladder, and prostate cancers." (PMID 23241148, 2012). "Thus, the LPXN interaction with CaD might regulate actin-cytoskeletal remodeling during prostate cancer progression." (PMID 26079947, 2015). "We validated the expression levels of 5 prognostic genes in the TCGA-PRAD and found that both ATCAY and GLUL were lower expressed in the tumor tissues than normal prostate tissues, while the ASNS, CAD and FPGS were overexpressed in the prostate cancer group." (PMID 36983244, 2023).
Sepsis (3 papers, 2019 to 2022). Sepsis is defined as life-threatening organ dysfunction caused by a dysregulated host response to infection. "Overall, CaD alleviates renal dysfunction and inflammation by targeting NF-κB signaling in sepsis-associated AKI." (PMID 35038964, 2022). "Overall, our results suggest that CaD has the potential to be considered for therapeutic use in the treatment of renal inflammatory damage and sepsis-induced AKI." (PMID 35038964, 2022). "In this study, we investigated the anti-inflammatory mechanism of CaD during phorbol 12-myristate 13-acetate (PMA)-induced monocyte-to-macrophage differentiation in in vitro models of sepsis (LPS) and hyperglycemia, using THP-1 monocytic cell line." (PMID 34829669, 2021).
virus infection (3 papers, 2018 to 2020). "However, little is known about the role of CAD during virus infection, and particularly the role of CAD in the EBOV life cycle still needed to be further analyzed." (PMID 32370067, 2020). "Two of these three factors, i.e., CAD and NXF1, were also remarkable insofar as all examined siRNAs targeting these factors showed a strong reduction in reporter activity following reporter virus infection." (PMID 30081931, 2018).
developmental delay (2 papers, 2021 to 2022). "EIEE-50, caused by a CAD mutation, will lead to intractable epilepsy, developmental delay or regression, and anemia in children." (PMID 35356445, 2022).
glioma (2 papers, 2020 to 2022). A benign or malignant brain and spinal cord tumor that arises from glial cells (astrocytes, oligodendrocytes, ependymal cells). "Supposedly, CAD and its upstream genes in glutamine metabolism would be potential targets in the therapy of patients with IDH-mutated glioma." (PMID 36568190, 2022). "To validate the conclusion further, we retrieved the RNA-sequence data of patients with glioma in CGGA, showing that high expression of CAD had a poor prognosis." (PMID 36568190, 2022).
head and neck squamous cell carcinoma (2 papers, 2020 to 2022). A squamous cell carcinoma that arises from any of the following anatomic sites: lip and oral cavity, nasal cavity, paranasal sinuses, pharynx, larynx, and salivary glands. "The Suzuki group further modified the CAd-VECPDL1 vector by incorporating IL-12 (CAdVECIL12_PDL1) and tested it in a head and neck squamous cell carcinoma (HNSCC) model." (PMID 35756634, 2022).
lymph node metastasis (2 papers, 2021 to 2022). "Clinical specimen results confirmed that the risk model established was effective, and the different expression pattern of ASNS and CEBPA was correlated with TNM stage and lymph node metastasis, whilst that of CAD was correlated with post-operative tumor metastasis and recurrence." (PMID 35174151, 2022).
mesothelioma (2 papers, 2025). A usually malignant and aggressive neoplasm of the mesothelium which is often associated with exposure to asbestos. "Analysis of ChIP-Seq data from mesothelioma cell lines indicated that both CAD and DHODH are potential targets of the YAP-TEAD1 transcriptional complex (Fig. EV6E,F)." (PMID 40707702, 2025). "Indeed, we observed that H2052 mesothelioma cells carrying NF2 mutations, exhibited higher levels of CAD and DHODH compared to normal cells and other PM cell lines with wild-type NF2." (PMID 40707702, 2025).
Nephropathy (2 papers, 2020 to 2021). A nonspecific term referring to disease or damage of the kidneys. "In addition, our experiments show that CaD prevents the increase and upregulation/activation of several pro-inflammatory cytokines (IL-6, CXCL1, IL-1ß, TNF-α, and MCP-1) that play a significant role in renal-disease progression." (PMID 31935212, 2020).
neuropathy (2 papers, 2020 to 2021). A disorder affecting the nervous system that manifests with pain, tingling, numbness, and/or muscle weakness. "Moreover, CaD reduced VEGF signaling in mice diabetic kidneys and ameliorated diabetic nephropathy and neuropathy, suggesting CaD as a VEGF inhibitor without the negative effects of complete VEGF blockade and therefore could be useful as a strategy in treating diabetic nephropathy." (PMID 31935212, 2020).
adenoma (1 paper, 2017). A neoplasm arising from the epithelium. "CaD strongly stained in the tumor stroma (branch-shaped appearance), with positive staining also evident in the cytoplasm of some adenoma cells of BD-NFPA specimens." (PMID 29235490, 2017). "Likewise, OPN had an elevated expression level in tumor stroma as well as in adenoma cells of BD-NFPAs cases, with CaD and OPN levels showing a positive correlation." (PMID 29235490, 2017).
brain tumor (1 paper, 2015). "We also studied the effect of Picalm knockdown in the murine CAD (Cath-a-differentiated) neuronal cell line, a central nervous system catecholaminergic cell line established from a mouse brain tumor." (PMID 26075887, 2015).
celiac disease (1 paper, 2016). An autoimmune genetic disorder with an unknown pattern of inheritance that primarily affects the digestive tract. "HSP90AA1, MKKS, EZR, HSPA14, APOB and CAD are proteins that involved in protein networks of celiac disease and have been determined as seeds." (PMID 27895852, 2016).
chronic kidney disease (1 paper, 2019). Impairment of the renal function secondary to chronic kidney damage persisting for three or more months. "Thus, we hypothesized that CaD is angioprotective and is a promising candidate for the treatment of chronic kidney diseases." (PMID 31447680, 2019).
chronic venous insufficiency (1 paper, 2022). Chronic form of venous insufficiency (disease). "CaD is a vascular-protective drug with beneficial effects for vascular diseases, such as chronic venous insufficiency, hemorrhoids, DR, and multiple microangiopathic diseases." (PMID 36340967, 2022).
coronary artery disease (1 paper, 2019). "Similarly, a recent metabolomics study reported a 12% decreased risk of coronary artery disease (CAD) among female human subjects associated with the genetic variant Rs715, which impairs function of the mitochondrial enzyme carbamoyl phosphate synthase (CPS)." (PMID 30916479, 2019).
diabetic nephropathy (1 paper, 2020). "We suggest a novel mechanism to interfere with VEGF signaling and suggest that the class of CaD compounds should be investigated further, particularly in the pathogenesis of diabetic nephropathy." (PMID 31935212, 2020). "We could also show that CaD ameliorates diabetic nephropathy in a streptozotocin-induced diabetic mouse model by VEGF inhibition." (PMID 31935212, 2020).
dyserythropoietic anemia (1 paper, 2025). "This condition is a progressive and severe metabolic disorder caused by biallelic deleterious variants in CAD gene, and is characterized by long seizures, psychomotor regression, and dyserythropoietic anemia." (PMID 40277802, 2025).
esophageal carcinoma (1 paper, 2012). A primary or metastatic malignant neoplasm involving the esophagus. "Recent studies have shown that higher gene expression of CaD, methylenetetrahydrofolate reductase, and multidrug-resistance protein 1 was associated with a response to chemotherapy in esophageal carcinoma." (PMID 23241148, 2012).
Hypertension (1 paper, 2021). The presence of chronic increased pressure in the systemic arterial system. "We found that genes related to hypertension—such as ACE, ANG, CAD, BMPR2, and other genes—were also significantly expressed in ascending aortic dissection tissue reported in the literature." (PMID 34262602, 2021).
injury (1 paper, 2022). Damage inflicted on the body as the direct or indirect result of an external force, with or without disruption of structural continuity. "Future study endeavors are required to investigate the precise regulatory mechanisms of how CaD exerts its functions against LPS-induced kidney injury by NF-κB signaling." (PMID 35038964, 2022).
lymphoma (1 paper, 2024). A malignant (clonal) proliferation of B- lymphocytes or T- lymphocytes which involves the lymph nodes, bone marrow and/or extranodal sites. "We next addressed the role of CAD in the proliferation and tumorigenesis of KSHV latent-infected endothelial cells and lymphoma cells." (PMID 38365882, 2024).
megaloblastic anemia (1 paper, 2025). Anemia characterized by the presence of unusually large erythroblasts in the bone marrow called megaloblasts. "For instance, CAD encodes a multifunctional enzyme of which biallelic mutations cause megaloblastic anemia, while heterozygous LoFs increase both MCH and RDW." (PMID 39896538, 2025).
multiple sclerosis (1 paper, 2022). A progressive autoimmune disorder affecting the central nervous system resulting in demyelination. "In contrast to CAD inhibitors, several DHODH inhibitors including brequinar (BRQ) and teriflunomide as well as its prodrug leflunomide have reached market approval as immunosuppressive agents in rheumatoid arthritis and multiple sclerosis." (PMID 35203388, 2022).
Obesity (1 paper, 2023). Accumulation of substantial excess body fat. "It is also important to note that the novel EC proteins, APP, CAD, BRD2 (which is part of DKFZp313H139), CST3, GRN, PPM1G and ZC3H4, have all been reported to be positively associated with obesity or adiposity, whilst the novel EC protein SLC25A24 may even prevent obesity and promote leanness." (PMID 37760635, 2023).
paraganglioma (1 paper, 2018). A benign or malignant neoplasm arising from paraganglia located along the sympathetic or parasympathetic nerves. "Paragangliomas with high levels of Clllow were found to contain low levels of CAD and p18." (PMID 29880867, 2018).
primary effusion lymphoma (1 paper, 2024). A large B-cell lymphoma located in the body cavities, characterized by pleural, peritoneal, and pericardial fluid lymphomatous effusions and that is always associated with human herpes virus-8 (HHV-8). "Collectively, our data indicate that targeting CDK6 and CAD is a promising strategy against γ-herpesvirus-induced primary effusion lymphomas." (PMID 38365882, 2024). "Correspondingly, genetic depletion or pharmacological inhibition of CDK6 and CAD potently impeded KSHV lytic replication and thwarted tumorigenesis of primary effusion lymphoma (PEL) cells in vitro and in vivo." (PMID 38365882, 2024). "In the KSHV-positive primary effusion lymphoma (PEL) cell line BCBL-1, depletion of CAD by CRISPR/Cas9 near-abolished cell proliferation in vitro, which can be partially rescued by the expression of RelA-DD." (PMID 38365882, 2024).
pulmonary arterial hypertension (1 paper, 2025). Pulmonary arterial hypertension (PAH) is a group of diseases characterized by mean pulmonary artery pressure >20 mmHg and elevated pulmonary arterial resistance leading to right heart failure. "CNP/cGMP signaling counteracts metabolic reprogramming in pulmonary arterial hypertension pericytes by reducing HIF1α, GLUT-1, and CAD activity, thereby normalizing glycolysis and pyrimidine synthesis and limiting hyperproliferation, highlighting its therapeutic potential." (PMID 40796654, 2025).
smooth muscle tumor (1 paper, 2015). A benign or malignant myomatous neoplasm arising from smooth muscle. "h-CaD has been reported to have tumor-supporting as well as tumor-suppressing functions and is also used as a diagnostic marker for smooth muscle tumors." (PMID 26079947, 2015).
tumor (67 papers, 2008 to 2026). "Here, cancer cell-intrinsic itaconate biosynthesis by cis-aconitate decarboxylase (ACOD1 or CAD, encoded by immune-responsive gene 1, Irg1) is shown to facilitate tumor immunogenicity and anti-tumor immunity." (PMID 39349845, 2024). "Here, we show that increased tumor-intrinsic cis-aconitate decarboxylase (ACOD1 or CAD, encoded by immune-responsive gene 1, Irg1) expression and itaconate production promote tumor immunogenicity and anti-tumor immune responses." (PMID 39349845, 2024). "l-CaD was consistently expressed in the cancer-associated stroma of all cases, suggesting a role in modulating the tumor microenvironment." (PMID 36768598, 2023). "An important role of CaD in multiple types of cancer is highlighted by the finding of tumor-specific splicing variants of the CALD1 gene in cancer tissues including colon, urinary bladder, and prostate cancer." (PMID 36768598, 2023). "Aberrant overexpression of carbamylphosphate synthetase 1 (CPS1) and SLC25A13 (citrin) genes has been associated with faster proliferation of tumor cells due to metabolic reprogramming that increases the activity of the CAD complex and pyrimidine biosynthesis." (PMID 37047726, 2023). "Positive expression of CAD was significantly associated with adverse pathological characteristics, including large tumor size (≥3 cm), lymphovascular invasion, intravesical therapy, higher stage, and grade." (PMID 26430961, 2015). "Importantly, mutations related to Asp1371 of CAD are found in tumor samples that failed neoadjuvant chemotherapy and pharmacological targeting of CAD-Asp1371 mutations using RMY-186 ameliorates chemotherapy efficacy." (PMID 40442064, 2025). "The consistent expression of l-CaD in the tumor stroma is in line with previous reports, which showed that l-CaD is expressed in the cancer-associated fibroblasts (CAFs) and other stromal cell populations where it plays a major role in the tumor microenvironment." (PMID 36768598, 2023). "The data revealed a decrease in tumor growth in the CAD-knockdown cell-derived xenograft mouse model compared with the control (SC vs shRNA1#, P < 0.01; SC vs shRNA3#, P < 0.001)." (PMID 40289107, 2025). "Therefore, although CAD mutations were present in only a very small percentage of all patients and were difficult to detect through unbiased, universal, and large-scale Sanger sequencing, they may dominantly determine the chemosensitivity of tumor tissue." (PMID 40442064, 2025). "Since normal, quiescent cells predominantly rely on salvage pathways for nucleotide biosynthesis, targeting DHOase or the CAD complex offers a strategy to selectively inhibit tumor cells while sparing healthy tissues." (PMID 39941127, 2025). "The upregulation of CAD facilitates tumor growth by ensuring a continuous supply of pyrimidine nucleotides." (PMID 39941127, 2025). "Western blotting further validated a marked decrease in ASS1 protein levels and a concomitant upregulation of CAD expression in tumor tissues derived from the sh‐CD2 group." (PMID 40859981, 2025). "Mechanistically, CAd-infected MSCs facilitated the spread of the oncolytic virus within the tumor microenvironment, leading to the release of IL-12 and the PD-L1 blocker." (PMID 40643499, 2025). "Consistent with murine data, CAD KO in PANC1 cells sensitized tumor cells to macrophage-mediated phagocytosis." (PMID 41243973, 2025). "As such, tumor-targeting CAD specific inhibitors that inhibit both protein deamidation and de novo pyrimidine synthesis remain to be developed for metabolic interventions against KSHV-associated malignancies." (PMID 38365882, 2024). "In the PPI network, DHODH was found to interact with UMPS and CAD to form enzyme complexes, facilitating pyrimidine biosynthesis in cells, thereby promoting DNA synthesis to regulate tumor cell proliferation and inhibit ferroptosis." (PMID 38796629, 2024).